KLK7 (kallikrein related peptidase 7)
Diseases named in the same sentence as KLK7 in open-access papers (continued):
Sharing a sentence is not in itself a finding about the gene and the disease.
atopic dermatitis (13 papers, 2010 to 2025). "Human tissue kallikrein-relatedpeptidase 7 (KLK7) is a serineprotease implicated in the physiology of skin desquamation, and itsuncontrolled activity can lead to chronic diseases such as psoriasis,atopic dermatitis, and Netherton syndrome." (PMID 38886921, 2024). "The expression level of kallikrein-related peptidase 7 (KLK7), an atopic dermatitis-associated serine protease, was elevated approximately 8-fold in the LBE group (61,577 ± 1080/2 × 107 pixels) compared to that of the control group (6771 ± 399/2 × 107 pixels)." (PMID 34946332, 2021). "Importantly, the upregulation of KLK5 and KLK7 activity by loss of the endogenous KLK inhibitor serine peptidase inhibitor Kazal type 5 (SPINK5) causes atopic dermatitis‐associated diseases, including Netherton syndrome." (PMID 29311134, 2018). "Although the roles of KLK5 and KLK7 in inflammatory dermatoses like Netherton syndrome and atopic dermatitis have been revealed, their functions in wound healing are still unclear." (PMID 40147022, 2025). "A monoclonal bispecific human anti-KLK5/KLK7-Fab antibody improved skin barrier function and reduced inflammation in mouse models of NS and atopic dermatitis." (PMID 41516101, 2025). "In summary, this workdemonstrated potential agents targeting KLK7 that can provide newstrategies for treating atopic dermatitis and other diseases relatedto skin desquamation." (PMID 38886921, 2024). "KLK7 was previously shown to induce inflammation, and increased KLK7 expression in the epidermis of atopic dermatitis patients was observed." (PMID 38731895, 2024). "Overall, the combination of animal studies with ABPs enabled the validation of KLK7 as a druggable target for NS and potentially other skin pathologies that share common molecular mechanisms, such as atopic dermatitis." (PMID 35631563, 2022). "The expression level of KLK7, a physiological activator of caspase 14, and the enzyme initiating the degradation of filaggrin, is mostly increased in human and murine atopic dermatitis tissues." (PMID 34946332, 2021). "Similarly, Klk7 overexpression results in epidermal thickening and dermal inflammation resembling atopic dermatitis." (PMID 40753921, 2025). "In particular, the skin-derived KLK5, KLK7, and KLK14 have recently gained increasing attention as promising therapeutic targets in inflammatory skin disorders and cutaneous malignancies, such as the widespread atopic dermatitis and the rarer Netherton syndrome." (PMID 41516101, 2025).
Netherton syndrome (13 papers, 2010 to 2025). Netherton syndrome (NS) is a skin disorder characterized by congenital ichthyosiform erythroderma (CIE), a distinctive hair shaft defect (trichorrhexis invaginata; TI) and atopic manifestations. "In this study, we revealed the in vivo roles of KLK5 and KLK7 using a set of mouse models that are simultaneously deficient for KLK5 and KLK7 on the genetic background of Netherton syndrome-like mouse model based on a mutation found in human patients." (PMID 28095415, 2017). "For example, a bispecific anti-KLK5/7 Fab antibody was raised against murine KLK5 and KLK7 with the potential to treat Netherton syndrome (NS)." (PMID 41516101, 2025). "In this direction, a skin equivalent (encompassing both epidermis and dermis) for SPINK5-sEDD (Netherton syndrome) was previously designed, to test the role of KLK7 and KLK5 gene silencing, or their chemical inhibition in reversing the disease phenotype." (PMID 40943523, 2025). "Targeted protease inhibition (KLK5/KLK7 blockade): If someone has Netherton syndrome, it means they lack the LEKTI protein, which leads to KLK5 and KLK7 acting uncontrollably and causing the skin barrier to break and become inflamed." (PMID 40734872, 2025). "SPINK5 specifically inhibits KLK5, KLK7, and KLK14 activity, and mutations in SPINK5 cause Netherton Syndrome, a severe skin disorder." (PMID 28414719, 2017). "LEKTI can diminish the activities of epidermal serine proteases such as KLK5, KLK6, KLK7, KLK13, and KLK14 in skin, and a mutation in the SPINK5 gene is characteristic of Netherton syndrome, which presents with serious dehydration, itching, and chronic skin inflammation." (PMID 35955819, 2022). "Building on previous work showing the clinical potential of targeting Klk5 in Netherton syndrome, our work establishes KLK7 and ELA2 as promising targets for the treatment of Netherton syndrome patients through the activation of NRF2 and subsequent upregulation of SLPI." (PMID 32457102, 2020).
Obesity (13 papers, 2013 to 2025). Accumulation of substantial excess body fat. "It counteracts inflammation and oxidative stress in inflammatory skin diseases, obesity, and associated metabolic disorders, in part by inhibiting the kallikrein proteases KLK7 and KLK14." (PMID 40975878, 2025). "Overall, these studies suggest that KLK7 is involved in the metabolic dysfunctions associated with obesity, particularly in terms of insulin action." (PMID 40427653, 2025). "Yet, in the constitutional knockout, the protective effects of Klk7 deficiency against obesity-associated adipose dysfunction and subsequently insulin resistance under HFD can be mainly attributed to lower fat mass (both, of eWAT and iWAT)." (PMID 33572949, 2021). "In conclusion, our data indicate potential application of specific KLK7 inhibitors to regulate KLK7 activity in the development of obesity and counteract obesity-associated inflammation and metabolic diseases." (PMID 33572949, 2021). "The protective effects of Klk7 deficiency in obesity are likely linked to a significant limitation of adipocyte hypertrophy." (PMID 33572949, 2021). "Such beneficial effect was linked to the inhibition of KLK7 (Kallikrein-Related Peptidase 7) which is up-regulated in obesity-induced insulin resistance patients." (PMID 31531264, 2019). "In accordance with vaspin transgenic (tg) mice, AT Klk7 deficiency revealed the most striking differences between the genotypes under the condition of high fat diet-induced obesity." (PMID 28932870, 2018). "Taken together, by attenuating adipose tissue inflammation, altering adipokine secretion and epigonadal adipose tissue expansion, Klk7 deficiency in adipose tissue partially ameliorates the adverse effects of HFD-induced obesity." (PMID 28932870, 2018). "KLK7 is also associated with tumor progression in various cancer types and may therefore be considered a treatment target for a variety of diseases including those related to obesity." (PMID 33572949, 2021). "While providing evidence for a novel and previously unrecognized role of KLK7 in adipose tissue and obesity-associated inflammation, the clear limitation of this study is that the physiological substrates of KLK7 in AT which contribute to the observed phenotype remain unknown." (PMID 28932870, 2018). "We have recently shown that ablation of the serine protease kallikrein-related peptidase 7 (Klk7) specifically in adipose tissue preserves systemic insulin sensitivity and protects mice from obesity-related AT inflammation." (PMID 33572949, 2021). "Vaspin targets the serine protease KLK7 and the regulation of proteolytic activity represents an integral component of vaspins’ protective effects in obesity." (PMID 33572949, 2021). "Expression of vaspin as well as knockout of KLK7 in adipose tissue has been shown to counteract local and systemic inflammation in obesity." (PMID 32344508, 2020). "Research that was carried out by Zieger at al. on the experimental model of obesity provided the first evidence of a significant contribution of KLK7 to glucose metabolism." (PMID 32917052, 2020). "Protease KLK7 degrades vaspinand is important for inflammation in adipose tissue, which is responsible for the development of obesity and insulin resistance." (PMID 30678306, 2019). "In summary, our studies demonstrate that KLK7 plays an important role in AT inflammation in HFD-induced obesity and insulin resistance." (PMID 28932870, 2018). "We propose KLK7 as a potential target and suggest (small compound) KLK7 inhibitors as promising therapeutic tools to improve obesity-related metabolic disorders." (PMID 28932870, 2018). "Additionally, emerging evidence points toward a potential role of the kinin-kallikrein system, particularly kallikrein 7 (KLK7), in obesity-associated insulin resistance." (PMID 40427653, 2025). "Notably, kallikrein 7 (KLK7) has garnered attention due to its role in insulin metabolism and obesity-related phenotypes." (PMID 40427653, 2025).
Obesity (continued). "Application of these molecules to Klk7−/− mice may further improve our understanding of KLK7-related or -dependent mechanisms in AT function and obesity development." (PMID 33572949, 2021). "Furthermore, knockout of KLK7 in adipose tissue preserved insulin sensitivity in obesity by counteracting adipose tissue inflammation under high-fat diet in vivo." (PMID 32344508, 2020). "Additionally, new research suggests that obesity affects the immune system and specific proteins like kallikrein 7 (KLK7), which may interfere with insulin’s ability to regulate blood sugar." (PMID 40427653, 2025). "Interestingly, chemerin was only detected in iWAT of Klk7−/− mice with diet induced obesity." (PMID 33572949, 2021). "But, although it has been suggested that Klk7 may mediate beneficial effects of recombinant vaspin in mouse models of obesity and diabetes, the role of KLK7 in adipose tissue has not been systematically studied in vivo yet." (PMID 28932870, 2018).
colon cancer (12 papers, 2012 to 2025). "KLK6 and KLK7 have been reported as markers of gastric, breast, and colon cancers and may be associated with m7G modifications." (PMID 37575065, 2023). "KLK7 is also associated with reduced survival times in ovarian, breast and colon cancer." (PMID 26231762, 2015). "In vitro, KLK7 overexpression in HT29-D4 human colon cancer cells significantly enhanced cell proliferation, colony formation, migration, spheroid formation, and adhesion to extracellular matrix proteins." (PMID 41335524, 2025). "For example, overexpression of KLK7 is found to stimulate colon cancer cell proliferation both in vivo and in vitro." (PMID 34395235, 2021). "Recently, several other members of KLK family like KLK7 have shown promise as potential biomarkers for various cancers including colon cancer." (PMID 22496748, 2012). "Moreover, overexpression of KLK7 in colon cancer cell lines promotes proliferation and tumorigenicity." (PMID 26231762, 2015). "Indeed, KLK7 was previously shown to induce inflammation and keratinocyte proliferation in the epidermis and a recent study identified KLK7 as a proliferative factor in a mouse model of colon cancer and in human cells in vitro." (PMID 28095415, 2017). "Colon cancer had four up-regulated KLKs with excellent AUC values (KLK6: 0.988, KLK7: 0.939, KLK8: 0.928, KLK10: 0.905)." (PMID 29707153, 2018). "Three kallikreins, KLK6, KLK7, and KLK8, were found to be overexpressed in colon cancer." (PMID 36293321, 2022).
Insulin resistance (11 papers, 2013 to 2025). Increased resistance towards insulin, that is, diminished effectiveness of insulin in reducing blood glucose levels. "These discrepancies between scientific findings highlight the need for further research to clearly define the relationship between the vaspin–KLK7 axis and the progression of insulin resistance." (PMID 41463050, 2025). "On top of that, vaspin prolonged the insulin half-time by inhibiting KLK7, which naturally helps mitigate insulin resistance." (PMID 41463050, 2025). "In adipose tissue, protease inhibition by vaspin is likely a major contributing mechanism to modulate inflammation, as knock out of target protease KLK7 in adipose tissue significantly reduced adipose tissue inflammation and insulin resistance in obese mice." (PMID 33866927, 2021). "Thus, KLK7 activity is thought to be a factor in the pathogenesis of systemic inflammation and insulin resistance in the course of obesity." (PMID 41463050, 2025).
psoriasis (10 papers, 2013 to 2025). An autoimmune condition characterized by red, well-delineated plaques with silvery scales that are usually on the extensor surfaces and scalp. "KLK-7, a serine protease involved in skin barrier functions, displayed a similar disease- and pharmacodynamic- relevance as IL-17A, prompting the consideration of its causal role in psoriasis manifestation and apremilast efficacy." (PMID 31953524, 2020). "As the main target protease of SerpinA12, KLK7 controls the process of the activation of pro-inflammatory IL-1β and prochemerin, all of which are involved in the pathogenesis of psoriasis." (PMID 39737188, 2024). "They identified IL17A and KLK7 as biomarkers for disease severity and apremilast pharmacodynamic effects in psoriasis patients." (PMID 35327421, 2022). "Following the initial exploration, we selected prominent analytes to understand the relationships of IL-17A and KLK-7 in psoriasis and LRG-1 in ankylosing spondylitis subjects, respectively." (PMID 31953524, 2020). "For broader validation, we surveyed KLK-7 mRNA expression patterns in human psoriasis subjects across public gene expression datasets with and without treatment." (PMID 31953524, 2020). "Using approximately 150 plasma analytes tracked across three time points, we identified IL-17A and KLK-7 as biomarkers for disease severity and apremilast pharmacodynamic effect in psoriasis patients." (PMID 31953524, 2020). "In psoriasis subjects, the combined score of IL-17A and KLK-7 was significantly downregulated after apremilast treatment." (PMID 31953524, 2020). "In psoriasis subjects, we identified IL-17A and KLK-7 as robust biomarkers to PASI total severity scores, which were significantly downregulated by apremilast, making the two biomarkers uniquely positioned to link disease- and apremilast- centric biology." (PMID 31953524, 2020). "We showed that the additive model of IL-17A and KLK-7 significantly captured more PASI score variability than univariate models in psoriasis." (PMID 31953524, 2020). "As an example for back-translation utilities, we propose to monitor IL-17A and KLK-7 protein levels as preclinical surrogates to estimate the effectiveness of next-generation psoriasis therapy." (PMID 31953524, 2020). "Upregulation of KLK-7 mRNA in peripheral and lesional skin was observed across multiple studies, consistent with the observed proteomic findings in the present psoriasis cohort." (PMID 31953524, 2020). "KLK7 also controls the enzymatic processing of antimicrobial peptide precursors in the skin and regulates the function of antimicrobial peptides, which act as immunomodulators in psoriasis." (PMID 39737188, 2024). "More specifically, we identified PEDF, MDC and ANGPTL4 from the same pharmacodynamic pattern as IL-17A and KLK-7, for which the combined rate of decline between Week 4 and 16 could differentiate apremilast clinical responses in psoriasis." (PMID 31953524, 2020). "While IL-17A was a well known marker, KLK-7 represented a novel psoriasis plasma biomarker." (PMID 31953524, 2020). "As a result, they recommended to use the combined expression rate of KLK7, PEDF, MDC, and ANGPTL4 in the patients’ blood to identify responders to apremilast among psoriasis patients." (PMID 35327421, 2022). "Experiments with mice showed an increase in KLK6, KLK7, and KLK8 mRNA levels when Psoriasis-like lesions were induced." (PMID 35356049, 2021). "Interestingly, two other approved therapeutics for psoriasis, broadalumab (anti-IL-17A) and etanercept (anti-TNF), also downregulate KLK-7 mirroring apremilast-induced effect, thus providing plausible explanations of converged therapeutic mechanism." (PMID 31953524, 2020). "Immunohistochemical studies have shown that the serine protease KLK7 and KLK14 is increased in psoriasis lesions compared to normal skin." (PMID 39737188, 2024).
psoriasis (continued). "The steeper combined reduction rate of PEDF, KLK-7, MDC, ANGPTL4 from Week 4 to 16 differentiated responders from non-responders in the psoriasis trial." (PMID 31953524, 2020). "However, the same experience conducted in KLK8 knockout mice did not result in KLK6 and KLK7 mRNA upregulation, suggesting a determinant role of KLK8 in proteolytic cascade in Psoriasis." (PMID 35356049, 2021).